PPP1R3D (protein phosphatase 1 regulatory subunit 3D)
Description:
Seems to act as a glycogen-targeting subunit for PP1. PP1 is essential for cell division, and participates in the regulation of glycogen metabolism, muscle contractility and protein synthesis.
Synonyms: PPP1R6
Tractability: PROTAC: ubiquitination databases record sites on it; its protein half-life has been measured.
Gene: Protein-coding gene on chromosome 20 (59,936,663 to 59,940,305, reverse strand). Ensembl gene ENSG00000132825.
Subcellular location (Human Protein Atlas): Calyx; Mitochondria; Vesicles; Connecting piece; Cytosol; Flagellar centriole; Mid piece; Nucleoli; Principal piece
Gene Ontology:
Molecular function: protein binding; glycogen binding; protein phosphatase 1 binding; protein serine/threonine phosphatase activity; phosphoprotein phosphatase activity
Biological process: regulation of glycogen biosynthetic process
Cellular component: protein phosphatase type 1 complex
Genetic constraint (gnomAD): Loss-of-function variants: 27 observed, 14.31 expected, observed/expected ratio (o/e) 1.89, 90% interval 1.32 to 1.97. The synonymous counts are far from expectation, so gnomAD's model fits this gene poorly and the ratio says little. Missense variants: 472 observed, 383.29 expected, observed/expected ratio (o/e) 1.23, 90% interval 1.14 to 1.33. Synonymous variants: 223 observed, 174.79 expected, observed/expected ratio (o/e) 1.28, 90% interval 1.14 to 1.43.
Homologues: Orthologues: chimpanzee PPP1R3D (99% identical), macaque PPP1R3D (96% identical), pig PPP1R3D (88% identical), dog PPP1R3D (87% identical), mouse Ppp1r3d (81% identical), rat Ppp1r3d (79% identical), tropical clawed frog ppp1r3d (50% identical), zebrafish ppp1r3da (37% identical), zebrafish ppp1r3db (36% identical), Caenorhabditis elegans H18N23.2 (21% identical), Drosophila melanogaster Gbs-70E (19% identical). Paralogues in human: PPP1R3E (33% identical), PPP1R3G (32% identical), PPP1R3A (24% identical), PPP1R3B (24% identical), PPP1R3F (24% identical), PPP1R3C (23% identical).
Diseases named in the same sentence as PPP1R3D in open-access papers:
PPP1R3D is named in the same sentence as 7 diseases in open-access papers, as found by Europe PMC text mining. Sharing a sentence is not in itself a finding about the gene and the disease. The quoted sentences say what the papers report.
asthma (2 papers, 2023 to 2025). "For example, genetically proxied expression of PPP1R3D was associated with disease characteristics of asthma, including mucosal immunity, cell metabolism, and airway remodeling, and predicted responsiveness to omalizumab therapy." (PMID 39794498, 2025).
myopia (2 papers, 2023 to 2024). "The results revealed that NR1D1, PPP1R18, PGBD2, and PPP1R3D genes were associated with myopia, and these genes were potential biomarkers for myopia." (PMID 39597899, 2024). "The biomarkers selected by both algorithms were plotted in a Venn diagram, and a total of 4 genes (NR1D1, PPP1R18, PGBD2, PPP1R3D) were identified as biomarkers of myopia in the overlapping part." (PMID 37740201, 2023). "Our study shows that NR1D1, PPP1R18, PGBD2, and PPP1R3D are effective as biomarkers in the diagnosis of myopia and that NR1D1, PPP1R18, PGBD2, and PPP1R3D may be potential therapeutic targets." (PMID 37740201, 2023).
Obesity (2 papers, 2011 to 2023). Accumulation of substantial excess body fat. "A number of novel obesity candidate genes were also identified (Thbs1, Ppp1r3d, Tmepai, Trp53inp2, Ttc7b, Tuba1a, Fgf13, Fmr) that have inferred roles in fat cell function." (PMID 21915269, 2011). "Interestingly, PPP1R3D has been reported as a novel obesity candidate gene." (PMID 38006387, 2023).
epilepsy (1 paper, 2022). A brain disorder characterized by episodes of abnormally increased neuronal discharge resulting in transient episodes of sensory or motor neurological dysfunction, or psychic dysfunction. "The PPP1R3D can regulate the structure of glycogen, and the deficiency of PPP1R3D preferentially inhibits neuronal and cardiac Lafora body formation in a mouse model of the fatal epilepsy Lafora disease." (PMID 36032143, 2022).
peanut allergies (1 paper, 2023). "Upregulated mRNA expression of PPP1R3D in blood cells is associated with IgE‐mediated peanut allergies in children." (PMID 38006387, 2023).
PPP1R3D also shares sentences with these, for which no sentence is quoted: anaphylaxis (1 paper); Lafora disease (1).